GALT (galactose-1-phosphate uridylyltransferase)
Diseases named in the same sentence as GALT in open-access papers (continued):
Sharing a sentence is not in itself a finding about the gene and the disease.
galactosemia (continued). "GALT enzyme activity was tested to determine optimal dietary options and was consistent with classic galactosemia (Gal‐1‐P Uridyltransferase <2.0 μmol/hr/mmol Hb, reference range > 18.5 μmol/hr/mmol Hb)." (PMID 31497475, 2019). "At 4 days of age, newborn screening revealed a mild increase in total galactose with normal galactose‐1‐phosphate uridylyl transferase (GALT) enzyme activity and all forms of Galactosaemia were excluded." (PMID 31441606, 2019). "Newborn screening can detect galactosemia by measurement of GALT enzyme activity and total galactose level." (PMID 31497475, 2019). "Classic galactosemia is a genetic disorder of galactose metabolism, in which there is a severe impairment of galactose-1-phosphate uridylyltransferase activity (GALT)." (PMID 28913702, 2018). "Increased oxidative stress has been reported in the fruit fly model of classic galactosemia, and superoxide dismutase-mimicking manganese-based compounds proved beneficial to GALT-null larvae and adult flies." (PMID 28281081, 2017). "In the specific case of classic galactosemia, a chaperone-based therapy would aim to mitigate GALT misfolding and aggregation, thereby enhancing GALT activity/stability." (PMID 28281081, 2017). "Congenital defects in GALT result in galactosaemia-1 or classic galactosaemia, congenital deficit of galactokinase causes galactosaemia-2 whereas GALE deficiency leads to a rare form of galactosaemia." (PMID 27707936, 2016). "The essentiality of this pathway is underlined by the group of genetic disorders known as galactosemia due to defects on the GALK1, GALT or GALE enzymes." (PMID 27005423, 2016). "White matter (WM) pathology has been repeatedly observed in classic galactosemia (OMIM 230400), an inherited disorder of galactose metabolism due to severe galactose-1-phosphate uridylyltransferase (GALT, EC 2.7.7.12) deficiency." (PMID 25344151, 2015). "GALT activity of classic galactosemia patients was significantly different from other groups with different variant alleles (p < 0.05)." (PMID 25124065, 2014). "All of the children with abnormal newborn screening results for galactosemia and reduced GALT activities started treatment with dietary galactose restriction." (PMID 25124065, 2014). "It has been reported that the frequency of GALT galactosemia has decreased in continental Europe, moving through populations in an eastern and southern direction." (PMID 25124065, 2014). "Classic galactosemia (CG; OMIM 230400) results from loss of galactose-1-phosphate uridyltransferase (GALT), the second enzyme in the Leloir pathway, which acts immediately downstream of galactokinase (GALK), the initial enzyme." (PMID 25326312, 2014). "Classic galactosemia (ORPHA79239) is caused by deficient activity of galactose-1-phosphate uridyl transferase (GALT), as a result of mutations in the GALT gene located on chromosome 9p13." (PMID 23866841, 2013). "Various missense mutations in GALK1, GALT, and GALE genes have been identified in patients with galactosemia." (PMID 19309526, 2009). "Indeed, we demonstrated significant efficacy of GALT mRNA in normalizing the disease-relevant biomarkers and restoring whole-body galactose oxidation in a mouse model of classic galactosemia." (PMID 41462863, 2025). "Here, we report the results of a small pilot study testing whether BMT with GALT+ donor cells might offer broad metabolic rescue in a rat model of classic galactosemia (CG)." (PMID 40656659, 2025). "In this study, we established that whole-body galactose oxidation (WBGO) as a robust, noninvasive, and specific method to assess the in vivo pharmacokinetic and pharmacodynamic parameters of two experimental gene-based therapies that aimed to restore GALT activity in a mouse model of galactosemia." (PMID 38352271, 2024). "Attenuation or lack of GALT activity leads to the disease classic galactosemia." (PMID 36788839, 2023).
galactosemia (continued). "Diagnostic erythrocyte galactose-1-phosphate uridylyltransferase (GALT) activity is expected to be absent or barely detectable in classic galactosemia, between 1 and 15% in clinical variant galactosemia, and between 15 and 25% in Duarte variant galactosemia." (PMID 37092512, 2023). "Classic galactosemia is characterized by severe GALT deficiency, the activity of the enzyme either lacking or being very poorly detectable at the level of erythrocytes and the liver." (PMID 36615667, 2022). "GALT, galactosemia type I, is the most common and severe form of galactosemia, affecting 1:16,000–60,000 people worldwide, and may manifest early, when a newborn takes the first milk meal, leading to IQ and behavioral/physical disabilities." (PMID 36004917, 2022). "The development of several animal models of classic galactosemia that (partly) mimic the biochemical and clinical phenotypes and the resolution of the crystal structure of GALT have provided important insights; however, precise pathophysiology remains to be elucidated." (PMID 33525536, 2021). "Notably, restoring GALT activity up to 10–15% is likely to rescue the phenotype in classic galactosemia." (PMID 33525536, 2021). "In type I, classic galactosemia (OMIM 230400), the conversion of α-d-galactose-1-phosphate (Gal-1-P) to α-d-glucose-1-phosphate (Glc-1-P) and uridine diphosphate-galactose (UDP-Gal) is hampered by the severe GALT deficiency." (PMID 33525536, 2021). "However, we found a number of VUS in such known genes, including ACADM, ACADVL and CFTR, and this has also been shown previously for other disease genes included in NBS panels, including PAH gene for phenylketonuria and GALT for galactosemia." (PMID 34449524, 2021). "This is suggested by in the so-called “biochemical variant galactosemia” where GALT activity levels between 10% and 15% do not result in clinical disease." (PMID 33525536, 2021). "Classical galactosemia is caused by the lack of GALT, which can result from the individual being homozygous or compound heterozygous for a pathogenic variant of the GALT gene." (PMID 33113773, 2020). "Classical Galactosemia (CG, OMIM 230400) is an autosomal recessive inborn error of galactose metabolism, caused by a deficiency of the enzyme galactose-1-phosphate uridylyltransferase (GALT, EC 2.7.7.12)." (PMID 32033562, 2020). "Classic galactosemia (CG, OMIM # 230400) is a rare inborn error of carbohydrate metabolism, caused by a severe deficiency of the enzyme galactose-1-phosphate uridylyltransferase (GALT, E.C. 2.7.7.12)." (PMID 31029175, 2019). "Failure of the GALT enzyme in galactosemia leads to accumulation of galactose in the body." (PMID 31497475, 2019). "In this example, we focus on galactosemia, a rare genetic metabolic disorder that is caused by a deficiency of one of the three enzymes GALK, GALT, and GALE (cf. pathway #3), which together constitute the so-called Leloir pathway converting galactose to UDP-glucose." (PMID 29921957, 2018). "Double GALT and GALK mutants or overexpression of UDP-Glc dehydrogenase corrected the glycosylation defects, the NMJ architectural alterations and the movement impairments associated with the Drosophila classic galactosemia model." (PMID 28281081, 2017). "Classic galactosemia (type I galactosemia, OMIM #230400) is caused by deficient activity of galactose-1-phosphate uridylyltransferase (GALT, EC 2.7.7.12), the second enzyme of the main pathway of galactose metabolism, the Leloir pathway, and its prevalence is 1:16,000-60,000 live-births." (PMID 28281081, 2017). "GALT deficiency results in the genetic disorder classic galactosemia, whose pathophysiology is still not fully elucidated." (PMID 25614870, 2014).
galactosemia (continued). "Classic galactosemia (OMIM #230400) is an autosomal recessive disorder caused by mutations in the GALT gene, resulting in deficient activity of galactose-1-phosphate uridylyltransferase (GALT, EC 2.7.7.12), a key enzyme in galactose metabolism." (PMID 25614870, 2014). "Classic galactosemia (OMIM #230400) is an autosomal recessive metabolic disorder caused by a deficiency of the galactose-1-phosphate uridyltransferase (GALT, EC2.7.7.12) protein due to mutations in the GALT gene." (PMID 25124065, 2014). "A five-year-old patient with galactosemia was referred for GALT gene sequencing." (PMID 24304607, 2013). "As galactose-1-phosphate uridyl transferase (GALT) enzyme analysis would have been noninformative due to previous erythrocyte transfusion during hospitalization, her GALT enzyme level was evaluated at age 3 months (72 U/L [n > 262]) and the diagnosis of galactosemia was confirmed." (PMID 24385729, 2012). "The second lesson of this case is that when total galactose metabolites are elevated, even if GALT activity is reported as relatively high, dietary intervention should not be delayed, especially if the baby shows early clinical signs consistent with classic galactosemia." (PMID 40352451, 2025). "From positive results with animal models, there is reason to hope that gene and mRNA therapy may restore human GALT activity in the future, but currently early detection followed by a lactose-restricted diet is the most effective treatment for classic galactosemia." (PMID 38778342, 2024). "Galactosemia is a genetic disease in which galactose accumulates in the body due to a deficiency of enzymes galactokinase (GALK), UDP-galactose 4-epimerase (GALE), and galactose-1-phosphate uridylyltransferase (GALT) involved in the metabolic process that converts galactose into glucose." (PMID 36900622, 2023). "Galactosemia is an autosomal recessive genetic disease that can be diagnosed at birth, even in the absence of symptoms, with newborn screening by assessing the level of galactose and the GALT enzyme activity, as GALT defect constitutes the most frequent cause of galactosemia." (PMID 35883524, 2022). "Galactosemia results in the deficiency of enzymes in the Leloir pathway including galactokinase (GALK1), galactose-1-phosphate uridylyltransferase (GALT), galactose mutarotase (GALM), or UDP-galactose 4′-epimerase (GALE), any of which can compromise the metabolism of galactose." (PMID 35118398, 2021). "Moreover, outcomes can differ even in siblings with the same GALT genotype, illustrating the complex nature of this condition with the presence of recognised significant epigenetic effects on the fundamental glycosylation pathways involved in galactosaemia." (PMID 30231941, 2018). "Whereas classic galactosemia has been hypothesized to result from GALT misfolding, a thorough functional–structural characterization of GALT most prevalent variants was still lacking, hampering the development of alternative therapeutic approaches." (PMID 25614870, 2014). "Genetic association of MRKH with galactosemia or with cystic fibrosis has been analysed but neither the gene for galactose-1-phosphate uridyl transferase (GALT) nor the gene encoding the CFTR chloride channel showed any mutation and/or polymorphism associated with Müllerian aplasia." (PMID 16441882, 2006). "Classic Galactosemia is a rare, autosomal recessive disease in which galactose is not metabolized properly due to severe deficiency/absence of the galactose-1-phosphate uridylyltransferase (GALT) enzyme, converting to an aberrant and toxic metabolite, galactitol." (PMID 35346295, 2022). "In addition, since several states and territories in the US have adopted the GALT mutation analysis as a second-tier test, it may be useful to expand the scope to other galactosemia-associated genes, including GALM, as another possible extension of neonatal screening for galactosemia." (PMID 34842598, 2021).
galactosemia (continued). "GALT activity levels in affected organs (brain, ovaries) do not seem to differ from the activity levels in organs not affected in classic galactosemia and distinct organ-specific levels of GALT activity have been found." (PMID 33525536, 2021). "We present two clinical cases of classical galactosemia diagnosed at the Lithuanian University of Health Sciences (LUHS) Kaunas Clinics hospital and we compare these cases in terms of clinical symptoms and genetic variation in the GALT gene." (PMID 33113773, 2020). "In this study, we aimed to extend our earlier in vivo POC work for an experimental GALT mRNA therapy for classic galactosemia from disease-relevant and functional biomarker normalization to disease-relevant phenotypes correction in a mouse model of galactosemia." (PMID 41462863, 2025). "Pathologically elevated blood galactose levels may occur because of deficient functioning of enzymes involved in galactose metabolism (e.g., GALK (galactokinase), GALT (galactose-1-phosphate uridyl transferase), or UDP-Galactose-4 epimerase (GALE)), a rare condition known as galactosemia." (PMID 31718111, 2019). "However, when it comes to gene-based therapies that are aimed to restore normal GALT activity in disease-relevant tissues, the in situ PK/PD assessments become challenging because the affected organs in galactosemia (i.e., liver, brain, and ovary) are not amendable to repeated sample collections." (PMID 38352271, 2024).
Sepsis (5 papers, 2022 to 2025). Sepsis is defined as life-threatening organ dysfunction caused by a dysregulated host response to infection. "The present study evidenced E. coli strains as the primary pathogen causing sepsis after CLP in GalT-KO mice and that removing anti-αGal antibodies with GAS914 boosted the killing of these pathogens, protecting animals from lethal infections." (PMID 37662909, 2023). "Genes such as CSF3, ELANE, F5, and GALT exhibited significant differential expression between sepsis patients and controls." (PMID 41194984, 2025). "The effect of removing anti-αGal antibodies in vivo was studied in GalT-KO mice submitted to CLP, which initially produces polymicrobial sepsis (2-12 h), shifting to predominant Gram-negative sepsis with coliform bacteria in the bloodstream at 24 h that causes, in most cases, animal death." (PMID 37662909, 2023).
cataract (3 papers, 2010 to 2025). Partial or complete opacity of the crystalline lens of one or both eyes that decreases visual acuity and eventually results in blindness. "The intracellular increase in galactitol induces hyperosmotic and oxidative stress which is responsible for the onset of cataracts in CG patients with GALT and GALK gene mutations." (PMID 39440457, 2024). "Galactitol accumulation inside cells causes their swelling and apoptosis, causing cataracts; moreover, high levels of galactitol were also detected in the brains of GALT‐deficient patients, which may play a role in the development of neurological symptoms, causing injury in Schwann cells." (PMID 39953772, 2025). "Finally, variations in at least eight genes underlying genetic forms of cataract (EPHA2, GJA8, GALT, SLC16A12, HSF4, GALK1, FTL, and CRYAA), and at least 10 other diverse genes have been associated to varying degrees with age-related cataract." (PMID 21042563, 2010).
cystic fibrosis (3 papers, 2006 to 2015). Autosomal recessive disorder caused by pathogenic variants in the CFTR gene (cystic fibrosis transmembrane conductance regulator), which encodes a chloride and bicarbonate channel expressed in epithelial cells, and follow the diagnosis criteria. "Specifically, despite being reliable for hemoglobinopathies, GALT and biotinidase enzymes as well as providing baseline testing for amino acids and acylcarnitines, admission testing may result in inaccurate TSH, 17-OHP, and cystic fibrosis (IRT) screening." (PMID 27057333, 2015).
GALE deficiency (3 papers, 2018 to 2025). "From 1968 to 2019, 30 cases with GALE deficiency were found with increased total galactose and normal GALT activity in Switzerland." (PMID 36056436, 2022).
endometriosis (2 papers, 2010 to 2011). The growth of functional endometrial tissue in anatomic sites outside the uterine body.
hepatocellular carcinoma (2 papers, 2018 to 2020). A malignant tumor that arises from hepatocytes. "Previously, we showed that knocking down GALT gene expression in the HepG2 cells by siRNA led to growth inhibition of the cultured hepatoma cells." (PMID 32028604, 2020). "Both GALK and GALT have recently been identified as prospective therapeutic targets in hepatocellular carcinoma." (PMID 30416487, 2018). "Interestingly, galactolysis has been recently suggested as the prospective therapeutic target for hepatocellular carcinoma, based on inhibition of galactokinase (GALK) or galactose-1 phosphate uridylyltransferase (GALT)." (PMID 30416487, 2018).
liver disease (2 papers, 2012 to 2023). "However TGAL may also be raised in DG, heterozygous CG carriers, neonatal liver disease and other rare inherited metabolic disorders, and therefore second‐tier analysis of galactose metabolites and GALT activity is used to increase specificity." (PMID 36873086, 2023).
adenomyosis (1 paper, 2022). The growth of endometrial tissue inside the muscular wall of the uterine corpus. "In addition, GALT mRNA expression was decreased in the eutopic endometrium (P = 0.014) of adenomyosis versus controls without significant changes in the myometrium (P = 0.282)." (PMID 35773139, 2022).
Age-related cataract (1 paper, 2022). A type of cataract (opacification of the lens) that forms during the course of aging. "At least 8 genes are known to be directly associated with age-related cataracts, including EPHA2, GJA8, GALT, SLC16A12, HSF4, GALK1, FTL, and CRYAA." (PMID 36107580, 2022).
Birk-Landau-Perez syndrome (1 paper, 2023). "Normal neuroimaging was observed in 12 (6.9%) individuals, including individuals with galactose-1-phosphate uridylyltransferase deficiency, SUCLG1 deficiency, Lesch-Nyhan syndrome, OPA3 deficiency, phosphatidylserine flippase deficiency, and Birk-Landau-Perez syndrome." (PMID 37810989, 2023).
colon cancer (1 paper, 2017). "TYMS, SHMT2, GALT, RENBP, and AMDHD2 were among the metabolic genes that had an unfavorable expression in colon cancer, meaning that their high expression in patients treated with 5-FU was associated with poorer prognosis." (PMID 29026541, 2017).
colorectal cancer (1 paper, 2017). A primary or metastatic malignant neoplasm that affects the colon or rectum. "In another study, a colorectal cancer–targeting antibody was GalT (Y289L) modified with azido-GalNAc which was then conjugated with two reporters." (PMID 29120405, 2017).
deafness (1 paper, 2022). An inherited or acquired condition characterized by the complete loss of the ability to hear from one or both ears. "Clinical manifestations are comparable to those in GALT deficiency, and they include nervous deafness and hypotonia." (PMID 36615667, 2022).
Failure to thrive (1 paper, 2025). Failure to thrive (FTT) refers to a child whose physical growth is substantially below the norm. "Hereditary galactosemia, such as galactose-1-phosphate uridylyltransferase deficiency, presents symptoms after milk intake, including failure to thrive, diarrhea, or other less common complications such as renal tubule dysfunction or cataract." (PMID 40003995, 2025).
G6PD deficiency (1 paper, 2024). An X-linked genetic condition caused by alterations in the gene G6PD that result in moderately to severely decreased activity levels of the enzyme glucose-6-phosphate dehydrogenase. "Other pilots have followed, each looking at possible conditions to be added to the NBS panel, including GALT and G6PD deficiency [1314,1315,1316,1317]." (PMID 38920845, 2024).